CNOT9 (CCR4-NOT transcription complex subunit 9)
Description:
Component of the CCR4-NOT complex which is one of the major cellular mRNA deadenylases and is linked to various cellular processes including bulk mRNA degradation, miRNA-mediated repression, translational repression during translational initiation and general transcription regulation. Additional complex functions may be a consequence of its influence on mRNA expression. Involved in down-regulation of MYB- and JUN-dependent transcription. May play a role in cell differentiation (By similarity). Can bind oligonucleotides, such as poly-G, poly-C or poly-T (in vitro), but the physiological relevance of this is not certain. Does not bind poly-A. Enhances ligand-dependent transcriptional activity of nuclear hormone receptors, including RARA, expect ESR1-mediated transcription that is not only slightly increased, if at all.
Synonyms: Rcd-1; RCD1; RQCD1; RCD1+; CT129; CAF40
Tractability: Small molecule: a structure with a bound ligand is known; it has a binding pocket of medium quality. PROTAC: ubiquitination databases record sites on it.
Gene: Protein-coding gene on chromosome 2 (218,568,580 to 218,597,080, forward strand). Ensembl gene ENSG00000144580.
Subcellular location: Nucleus; Cytoplasm, P-body
Subcellular location (Human Protein Atlas): Cytoplasmic bodies
Pathways (Reactome):
Developmental Biology: Activation of anterior HOX genes in hindbrain development during early embryogenesis; M-decay: degradation of maternal mRNAs by maternally stored factors
Metabolism of RNA: Deadenylation of mRNA
Gene Ontology:
Molecular function: epidermal growth factor receptor binding; kinase binding; protein binding; protein domain specific binding; protein homodimerization activity; transcription coactivator activity
Biological process: negative regulation of intracellular estrogen receptor signaling pathway; positive regulation of epidermal growth factor receptor signaling pathway; positive regulation of peptidyl-serine phosphorylation; negative regulation of translation; nuclear-transcribed mRNA poly(A) tail shortening; sex differentiation; mRNA catabolic process; positive regulation of DNA-templated transcription
Cellular component: CCR4-NOT complex; membrane; protein-containing complex; CCR4-NOT core complex; cytosol; nucleus; P-body
Genetic constraint (gnomAD): Loss-of-function variants: 7 observed, 25.12 expected, observed/expected ratio (o/e) 0.28, 90% interval 0.16 to 0.52. The upper end of that interval is the gene's LOEUF score, 0.52, which puts it in group 2 of 6, group 1 being the genes least tolerant of losing a copy. Missense variants: 136 observed, 315.27 expected, observed/expected ratio (o/e) 0.43, 90% interval 0.37 to 0.5. Synonymous variants: 105 observed, 124.33 expected, observed/expected ratio (o/e) 0.84, 90% interval 0.72 to 0.99.
Gene-disease validity (ClinGen):
ClinGen rates the evidence that CNOT9 causes each of these diseases.
complex neurodevelopmental disorder (autosomal dominant): Limited. A disorder that involves more than one phenotype associated with the central nervous system, including but not limited to intellectual disability, autism, and seizures (epilepsy).
Homologues: Orthologues: chimpanzee CNOT9 (100% identical), dog CNOT9 (99% identical), guinea pig CNOT9 (99% identical), mouse Cnot9 (99% identical), rabbit CNOT9 (99% identical), rat Cnot9 (99% identical), tropical clawed frog cnot9 (99% identical), zebrafish cnot9 (96% identical), pig CNOT9 (95% identical), Drosophila melanogaster Rcd-1 (75% identical), Caenorhabditis elegans ntl-9 (70% identical), Drosophila melanogaster Rcd-1r (58% identical).
Diseases named in the same sentence as CNOT9 in open-access papers:
CNOT9 is named in the same sentence as 8 diseases in open-access papers, as found by Europe PMC text mining. Sharing a sentence is not in itself a finding about the gene and the disease. The quoted sentences say what the papers report.
melanoma (6 papers, 2015 to 2023). A malignant, usually aggressive tumor composed of atypical, neoplastic melanocytes. "The functional oncogenic role of CNOT9/RQCD1 in melanoma remains currently unknown although limited studies revealed RQCD1 implication in AKT activation and cell proliferation." (PMID 32850962, 2020).
breast carcinoma (5 papers, 2012 to 2024). "CNOT9 is frequently up-regulated in human breast cancer specimens and cell lines, and its expression is extremely low in normal human tissues, except testis, which suggests that CNOT9 is a cancer antigen." (PMID 25191340, 2014). "Short hairpin RNA (shRNA)-mediated suppression of CNOT9 drastically suppresses the proliferation of breast cancer cells." (PMID 25191340, 2014). "CCR4-NOT transcription complex subunit 9 (CNOT9/RQCD1) has been identified as a key activator of the PI3K/AKT pathway, and upregulation of miR-361 in breast cancer cells can suppress its direct target RQCD1, leading to the downregulation of PI3K, AKT, and MMP-9." (PMID 31394811, 2019).
thymoma (1 paper, 2020). A neoplasm arising from the epithelial cells of the thymus. "Studies on mRNA‐seq data of thymoma confirm such notion by showing the correlation between the low levels of CNOT2/CNOT9 and the poor survival." (PMID 31967407, 2020). "It was inspiring to find that the expression of CNOT family (CNOT2 and CNOT9) and SHMT1 was highly correlated with the prognosis of thymoma: Patients with lower expression of these genes at transcription level had poor relapse‐free survival (RFS) probability." (PMID 31967407, 2020). "CNOT2, CNOT9, CD99, PRSS16, PSMB11, and SHMT1 were found with high abundance in thymoma and participated mainly in nucleic acid and amino acid metabolism." (PMID 31967407, 2020).
cancer (4 papers, 2014 to 2024). A tumor composed of atypical neoplastic, often pleomorphic cells that invade other tissues. "The Akt phosphorylation that is induced by EGFR signaling is attenuated in the absence of CNOT9, which suggests that CNOT9 enhances EGFR signaling and contributes to carcinogenesis and progression of cancer, particularly in mammary glands." (PMID 25191340, 2014).
CNOT9 also shares sentences with these, for which no sentence is quoted: tumor (3 papers); cutaneous melanoma (2); non-melanoma skin carcinoma (1); solar keratosis (1).